CD3D (CD3 delta subunit of T-cell receptor complex)
Diseases named in the same sentence as CD3D in open-access papers (continued):
Sharing a sentence is not in itself a finding about the gene and the disease.
tumor (continued). "Here, we performed a comprehensive analysis of CD3D in BRCA and the outcomes revealed a possible correlation between CD3D and tumor immune infiltration cells, immune checkpoints, and the mechanisms involved." (PMID 33350431, 2021). "We adjusted these results based on tumor purity, revealing strong and significant correlations between CD96 and CD8+ T cell markers (CD8A), general T cell markers (CD3D, CD3E, CD2), DC markers (HLA-DPB1, HLA-DRA, HLA-DPA1) in LGG." (PMID 33680972, 2021). "We next explored the association of the expression at an individual transcriptomic level of CD2, CD3D, CD3E, and CXRC6 with the presence of tumor-infiltrating immune cell populations." (PMID 34692491, 2021). "Additionally, TGFB2 methylation correlates inversely with numerous T cell receptor (TCR) signaling components—HLA-D molecules, CD3D, CD28, and LCK—all of which are upregulated in the tumor when TGFB2 is weakly methylated." (PMID 40650134, 2025). "Furthermore, H-151 not only inhibited the p-STING/p-IRF3 axis but also significantly reduced the expression of T cell infiltration and activation markers (CD3D and CD69) as well as anti-tumor factors (GZMB, IFNγ, and TNFα)." (PMID 40846839, 2025). "The cell type-specific markers we used for cell annotation were as follows: T cell (CD3D); NK cell (KLRD1 and NKG7); plasma cell (IGKC and JCHAIN); Mast cell (KIT and TPSB2); tumour cell (CA9, NDUFA4L2 and SLC17A3); endothelium (PECAM1, PTPRB and KDR); mesangial cell (ACTA2 and PDGFRB)." (PMID 40830065, 2025). "In sum, it could be inferred that CC cells undergoing necroptosis induced the expression of CD3D and up-regulated the JAK2-STAT3 signaling pathway in Jurkat cells, which might facilitate T cell activation and trigger anti-tumor immunity." (PMID 39247606, 2024). "In addition, CLDN18 also correlated significantly with markers of activated CD8 + T cells such as MPZL1, CSE1L, CD37, AHSA1, CD3D and IL2RB, after adjusting for tumor purity." (PMID 37438735, 2023). "The residual tumor contains 94.7% (430 cells) of C1 TAMs, which express CD7, CD3D and CD3E." (PMID 35784460, 2022). "We further investigated the expression of key DEeRNAs between tumor and normal samples among different cancer types and identified that the expression level of CCR1, CD3D, PHLDA1, and RASD1 was significantly up-regulated in tumor tissue, as compared with normal tissue." (PMID 36092920, 2022). "The clustering of T/NK cells of the tumor environment revealed 5 main populations, including NK/NKT subtype (GNLY and TRDC), γδ T cells (GNLY, TRDC, and CD3D), CD4+CD8+ T cell subtype (CD3D, CD8A, and CD4), CD8+ T cells (CD3D and CD8A), and CD4+ T cells (CD3D and CD4)." (PMID 35907904, 2022). "Based on bulk RNA data from the TCGA cohort, the highest levels of wild-type CYSLTR2 expression were observed in tumours with an inflammatory phenotype as shown by their immune gene expression signature (high expression of CD14, CD163 [monocytes/macrophages] and CD3D, CD8A [T cells])." (PMID 33588787, 2021). "CD3D and NFATC1 were the common genes in the three tumor data sets." (PMID 34794456, 2021). "In addition, we found a positive association between the gene expression level of CD2, CD3D, CD3E, and CXRC6 and the activated fraction of NK cells present in the tumor (CD2: Rho=0.442, CD3D: Rho=0.460, CD3E: Rho=0.423, and CXCR6: Rho=0.401)." (PMID 34692491, 2021). "Finally, we investigated the connection between tumor grades and hub genes, in which LCK, CD2, CD3D, IFNG, CD8A, and CCL5 showed significant correlation with different tumor grades (p < 0.05), with grade increase corresponding to increased gene expression." (PMID 32081834, 2020). "Previous studies determined the upregulation of genes related to immune cell activation (e.g., CD3D, CD8, CXCR3, CCL5, CXCL9, and CXCL10) in cancer patients with a better prognosis, thereby highlighting the impacts of immune-related genes on tumor progression." (PMID 32775427, 2020).
tumor (continued). "CD8+ T cell abundance was quantified from tumor RNAseq profiles using a four-gene expression signature score (referred to as TSIG) derived from the geometric mean of the normalized log2 read counts for the genes CD8A, CD8B, CD3D, and CD3E." (PMID 32117236, 2020). "EGFR and IDH1 were highly expressed in tumor cells, FAP and COL1A1 were confined to fibroblasts, CD68 and ITGAM marked macrophages, PECAM1 and CDH5 identified endothelial cells, OLIG2 and MOG were specific to oligodendrocytes, while CD4 and CD3D defined T-cell subsets." (PMID 41208987, 2025). "In total, five populations were designated tumour clusters, which had various features: (TumourC0) CD74 and APOD; (TumourC1) IF16, JUN and HSPA1A; (TumourC2) S100B and SCRG1; (TumourC3) NEAT1 and MALAT1; and (TumourC4) WFDC2 and RNASE1 (HLA‐DRA, CD68, CD3D, CD3E)." (PMID 37784253, 2023). "Additionally, functional annotation further suggested that CD3E, CD3D, and LCK were involved in positive regulation of T cell activation and leukocyte cell-cell adhesion that were known as the chief determinant for the efficacy of tumor immunotherapy." (PMID 33748188, 2021). "The six critical genes, including CCR7, FCGR2B, BTLA, CD6, CD3D and CD3E, play important roles in favoring tumor progression and promoting negative immune-regulatory effects." (PMID 36291815, 2022). "Then, the qRT-PCR and western blotting were applied to detect the expression differences of CD2, CD3D, and CD3E in tumor tissues from recurrence and no recurrence patients." (PMID 36146529, 2022). "Based on Oncomine database, we identified that expression of CCR1, CD3D, MAZ, PHLDA1, and RASD1 was higher in tumor than that in normal tissue at the pan-cancer level." (PMID 36092920, 2022). "The assessment of the new immune gene signature (CD2, CD3D, CD3E, and CXCRC6) in the CSCC cohort per tumor stage was not possible because sample size was too low for a meaningful analysis when we filtered data by stage." (PMID 34692491, 2021). "Compared with normal control tissues, the expression level of CD3D and CD2 in tumor tissues were not significantly different, while the expression levels of CD3E, CD3G, CCL5, CXCR6 and LCK in tumor tissues were lower than those in normal tissues (P < 0.05)." (PMID 34218795, 2021). "Modules 1–5 were rich in cytokines (e.g., IL6, IL10), cytokine receptors (e.g., CCR2, CCR4), and immune cell markers (e.g., CD3D, CD3E), indicating that the DEGs primarily regulate the immune microenvironment rather than tumor malignancy traits like proliferation and invasion." (PMID 38594692, 2024). "We could only detect the RNA and protein expression changes of CD3G, but not CD3D, CD3E or CD247 between tumor and normal tissues." (PMID 36176400, 2022).
cancer (61 papers, 2013 to 2025). A tumor composed of atypical neoplastic, often pleomorphic cells that invade other tissues. "CD3D is responsible for initiating T cell signal transduction and is associated with the antitumor immune response across various cancer types." (PMID 39845086, 2024). "Yin and colleagues stratified BC patients into high and low risk cancers based on a seven gene expression assay (BATF, CD3D, HLA-DQB2, JUN, MAP2K6, NFKBIE, PAK1)." (PMID 40148963, 2025). "Analysis of the TCGA database demonstrated significant associations between CD3D, CD3E, and CD3G expressions and several cancers, including CC (p < 0.05)." (PMID 40702236, 2025). "We found that single-cell RNA sequence data derived from patients with PDAC showed the expression level of HRH1 in cancer cells is negatively correlated with the expression level of CD3D+, CD8A+ T cells." (PMID 38715057, 2024). "It further shows that CD3D can be used as a key regulatory factor of immunotherapy response for cancer patients." (PMID 34093667, 2021). "In the gene co‐expression network, we observed that YRDC was associated with the expression of multiple immune cell signature genes at the pan‐cancer level, including T‐cell signature genes (CD3D, CD4, CD8A, CD8B), B‐cell signature genes (CD19, MS4A1), and multiple immunoglobulin genes." (PMID 40898423, 2025). "From these clusters, five major cell types were identified via classical cell markers, including T cells (CD3E, CD8A, CD3D), B cells (CD19, MS4A1, CD79A), myeloid cells (CD14, CD68, LYZ), endothelial cells (PECAM1, VWF, CDH5) and cancer-associated fibroblasts (CAFs) (ACTA2, FAP, PDGFRB)." (PMID 39941131, 2025). "Recent research has suggested that CD3D could be a predictive biomarker of the prognosis in some cancers 75,76." (PMID 39247606, 2024). "A pan-cancer analysis of CD3D expression level across various cancer types using data from TCGA was performed to investigate whether the protective effect of CD3D was limited to CC or applicable to other malignancies." (PMID 39247606, 2024). "Some markers CD14 (monocyte), CD3D (CD4+T cells), CD3E (CD8+T cells), CD68 (macrophage), CST3 (myeloid cells), GNLY (NK cells), KRT18 (epithelial cells), and NKG7 (NK cells) were positively associated with TMSB10 in all cancers." (PMID 37275863, 2023). "Briefly, myeloid cells (LYZ+), lymphocytes (CD3D+), osteoclasts (ACP5+), endothelial cells (CLDN5+), perivascular-like cells (PVL) (RGS5+TAGLNhigh), cancer-associated fibroblasts (CAFs) (TAGLNlowACTA2+) and proliferative cells (MKI67+) were identified in the study." (PMID 36596773, 2023). "The cells were further annotated as specific cell type subpopulations according to the expression of classic markers, including T cells (CD3D+), myeloid cells (CD68+), endothelial cells (CD34+), hepatocytes (ALB+), B cells (CD79A+), and cancer-associated fibroblasts (CAFs) (ACTA2+)." (PMID 37383234, 2023). "Moreover, the downregulation of CD3D in the peripheral blood of PCa patients undergoing EBRT was correlated with CD8+ T-cell suppressed responses leading to the development of cancer-related fatigue during radiation therapy." (PMID 36291815, 2022). "Hence, high expression of CD3D typically indicates better clinical prognosis for cancer patients." (PMID 38918587, 2024). "Prognostic correlations between CD3D, CD3E, and CD3G gene expressions and various cancers were analyzed using the Cancer Genome Atlas (TCGA) database." (PMID 40702236, 2025). "Through this analysis, we identified eight major cell types, namely B cell (CD79A), cancer cell (KRT5), cycling cell (MKI67), endothelial cell (VWF), fibroblast (COL1A1), mast cell (KIT), monocyte/macrophage (CD14) and T cell (CD3D)." (PMID 38279519, 2024). "Flow cytometry was performed to identify and collect the cancer cells marked by EPCAM, T cells marked by CD3D, CD8+ T cells marked by CD8A, and CD4+ T cells marked by CD4 in the GGN-ADC and SADC samples." (PMID 33083004, 2020).
cancer (continued). "In specific, TIS is referred to as an 18‐gene signature (CCL5, GZMK, CD3D, CD3E, CD2, HLA‐DRA, IL2RG, NKG7, CIITA, CXCR6, LAG3, TAGAP, HLA‐E, CXCL13, IDO1, CXCL10, STAT1, and GZMB), which was related to the response to ICIs in various cancers." (PMID 37434432, 2023). "According to the KEGG analysis, CHST11 may participate in PD‐L1 expression and PD‐1 checkpoint pathway in cancer by regulating genes TICAM2, LAT, TLR2, CD4, STAT3, NFKBIE and CD3D." (PMID 36062845, 2023). "Results of external validation in eRic database showed the specific chromatin localization and target genes of the four key DEeRNAs (CCR1, CD3D, PHLDA1, and RASD1), as well as potential drugs that may target these DEeRNAs in different cancers." (PMID 36092920, 2022). "Notably, cells of C8 subgroup were T cell-like cancer cells and expressed specific markers of T cells, such as CD7, CD3D, and CD3E." (PMID 36451812, 2022). "Similarly, genes involved in T cell mediated immune response, such as CD3D, CD3E, CD3G, CD247 in the CD3-TCR complex and downstream effector ZAP70, were more rapidly repressed in LUSC than in LUAD, especially at the early cancer stage." (PMID 27863400, 2017). "Similar with CD3D and CD52, CD79A and CD37 can not only help us monitor specific T–B interactions, which is one of the major parts of the anti-cancer immune response, but can also provide us a new biomarker to evaluate the alteration of cancer microenvironment during tumorigenesis." (PMID 34575089, 2021).
infection (14 papers, 2007 to 2025). The state of being infected such as from the introduction of a foreign agent such as serum, vaccine, antigenic substance or organism. "After infection, MP antigens stimulate and upregulate T cell surface molecules including CD3D, CD3E, CD3G, and CD8, followed by the upregulation of downstream molecules including CD3Z, FYN, LCK, ZAP70, GADS, P38, and ITK." (PMID 29967623, 2018). "Gene expression pattern in perigonadal fat at day 28 post-infection was distinct from subcutaneous fat where only Cd3d was upregulated." (PMID 29040326, 2017). "Following 7 days post infection, 92% of the cells expressed mCherry and eGFP when utilizing the dLck-promoter (left) whereas, 67% of the cells were double positive for mCherry and eGFP with lentivirus containing the CD3δ-promoter (right)." (PMID 32792615, 2020). "Cluster 3, which identified genes upregulated at day 7 post-infection, was highly enriched for T cell responsive genes, including those involved in T cell activation, lymphocyte proliferation, and TCR signaling, e.g. CD3D/E/G, CD8A/B, CD28, CD40LG, and GATA3." (PMID 38950078, 2024). "Infection with either strain increased expression of ISGs (GBP1, IFIT1, IRF7) and reduced expression of lymphocyte related genes (CD3D, CD8A, ZAP70)." (PMID 28852031, 2017). "Infection by HTLV-I has been shown to ultimately downregulate CD3γ, CD3δ, CD3ε, and CD3ζ gene transcripts leading to a CD3- surface phenotype after 200 days of in vitro infection; however, the sequence of gene loss has not been investigated." (PMID 17822534, 2007). "When comparing DEG in both SARS-CoV-2-infected groups at day 2 (i.e., 2 days after SARS-CoV-2-only infection and 4 days after H1N1 infection in the dual-infected group), only five known genes (Cd3d, Ctsw, Kirrel2, Osbpl1a and Aurkb) were differentially expressed at padj < 0.05." (PMID 38400021, 2024). "Expression of Cd3d, Cd8a, Ifn, Ccl5 and Tbx21 remained highly upregulated 56 days post-infection whereas Ccr7 did not." (PMID 29040326, 2017). "Strikingly, we found that the infection with HeV and NiV-B did not modify the expression levels of lymphocyte markers (CD2, CD3D, CD3E, CD3G, CD4, CD8A and CD27) in the lung tissue by 5 dpi." (PMID 29538374, 2018).
bacterial infections (1 paper, 2025). "Whereas Class2 uniquely included pathways related to bacterial infections (e.g., E. coli, Salmonella) together with actin-cytoskeleton and T-cell modules (e.g., ACTB, PFN1, RAC2, PIK3CD, CD3D/CD3G, STING1, TRADD, CASP8, BCL2, HLA-F)." (PMID 41394852, 2025).
CD3D also shares sentences with these, for which no sentence is quoted: ovarian carcinoma (4 papers); cervical squamous cell carcinoma (2); diabetes (2); lung adenocarcinoma (2); T cell lymphoma (2); acute leukemia (1); Allergy (1); Arthritis (1); ataxia telangiectasia (1); atherosclerosis (1); athymia (1); Autoimmunity (1); Bloom syndrome (1); Cerebral ischemia (1); coeliac disease (1); colitis (1); combined immunodeficiency (1); cutaneous malignant melanoma (1); dermatomyositis (1); dilated cardiomyopathy (1); endocervical adenocarcinoma (1); esophagus tumors (1); Fanconi anemia (1); fibrosis (1); gastric tumors (1); genetic disorders (1); Granuloma (1); head and neck cancer (1); hepatitis C (1); hepatocellular carcinoma (1).
A further 17 diseases each share a sentence with CD3D in 1 paper.